SDCBP (syndecan binding protein)
Diseases named in the same sentence as SDCBP in open-access papers (continued):
Sharing a sentence is not in itself a finding about the gene and the disease.
tumor (continued). "Intriguingly, the combined treatment of metformin and adenoviral SDCBP shRNA significantly enhanced the anti-tumor effects of metformin without decreasing body weight." (PMID 40263598, 2025). "Tumor-promoting candidates LAMA5, SDCBP and TENA were consistently upregulated in PDAC EVs." (PMID 35241737, 2022). "CAB012245 is an antibody against SDCBP, which showed a higher intensity in tumor tissue than in normal tissue." (PMID 33692827, 2021). "In melanoma, SDCBP facilitates the formation of active FAK/c-src signaling complexes and the activation of nuclear factor-kappa B (NF-κB) and matrix metalloproteinase (MMP) by directly interacting with c-src to promote tumor invasion and metastasis." (PMID 28141839, 2017). "In these tumors where the estrogen signaling pathway is not available, SDCBP probably contribute to tumor growth through an alternative signaling pathway by promoting tumor cells passing the G1/S checkpoint into the cell cycle." (PMID 23533663, 2013). "Intra-tumoral injection of the adenoviral SDCBP shRNA effectively suppressed SDCBP expression as well as 4T1 tumor growth, whereas treatment with metformin alone did not significantly suppress 4T1 tumor growth." (PMID 40263598, 2025). "Moreover, depleting SDCBP leads to upregulation of BACH1-repressed electron transport chain (ETC) genes, such as NDUFA4 and COX6B2, and increases mitochondrial activity, enhancing anti-tumor efficacy of metformin against TNBC both in vitro and in vivo." (PMID 40263598, 2025). "Therefore, the results of the nude mice tumor xenografts further confirmed that dasatinib blocks SDCBP overexpression-induced TNBC tumor growth, suggesting that dasatinib might be a targeted therapy for TNBCs that overexpress SDCBP." (PMID 28141839, 2017). "Dasatinib administration significantly inhibited tumor growth in nude mice inoculated with MDA-MB-231 cells, regardless of the presence of SDCBP overexpression." (PMID 28141839, 2017).
adenocarcinoma (1 paper, 2021). A common cancer characterized by the presence of malignant glandular cells. "Positive immunostaining was detected for SDCBP in adenocarcinomas." (PMID 34445387, 2021).
SDCBP also shares sentences with these, for which no sentence is quoted: infection (6 papers); colon cancer (4); colorectal cancer (3); head and neck squamous cell carcinoma (3); viral infection (3); acute myocardial infarction (2); cutaneous melanoma (2); heart failure (2); lung adenocarcinoma (2); retinal degeneration (2); Ataxia (1); breast neoplasm (1); colitis (1); cystitis (1); gastric ulcer (1); gastrointestinal disorders (1); HIV-1 infection (1); immune deficiency (1); irritable bowel syndrome (1); kidney cancer (1); laryngeal carcinoma (1); lung squamous cell carcinoma (1); metastatic cancer (1); metastatic melanoma (1); nasopharyngeal carcinoma (1); neurodevelopmental disorder (1); neuroendocrine tumors of the lung (1); neurological disorders (1); Obesity (1); prostate (1).
A further 12 diseases each share a sentence with SDCBP in 1 paper.